CLDN1 (claudin 1)
Diseases named in the same sentence as CLDN1 in open-access papers (continued):
Sharing a sentence is not in itself a finding about the gene and the disease.
breast carcinoma (continued). "Treatment of Michigan Cancer Foundation-7 (MCF-7) breast cancer cells with tamoxifen, a well-known anti-estrogen drug, increased claudin-1 expression." (PMID 32197343, 2020). "The authors showed that the protein expressions of CLDN-1 were significantly higher in the basal-like subtype of breast cancers (ER-ve, Her-2-ve, EGFR+ve, CK5/6+ve, a subtype largely linked to poor outcome." (PMID 31952355, 2020). "In summary, our data show that ADAM15 expression in breast cancer cells leads to upregulated expression of the tight junction protein Claudin-1, which involves activation of the PI3K/mTOR pathway." (PMID 31467400, 2019). "In breast cancer cells, overexpression of DEC1 promoted the invasiveness of breast cancer through downregulation of claudin-1." (PMID 30691465, 2019). "Claudin-1 has been regarded as a tumor suppressor in breast cancer due to its frequent down-regulation during tumor progression." (PMID 31717460, 2019). "Claudin-1 expression decreased in breast cancers, while its high expression was proved in thyroid, urothelial, gastric and cervical tumors." (PMID 31700829, 2019). "In basal-like breast cancer patients, the highest level of CLDN1 protein expression was observed in patients who were older than 55 years of age." (PMID 30910845, 2019). "Interference with DOCK1 expression by shRNA resulted in re-expression of claudin-1 in conjunction with significant inhibition of cell viability and motility of claudin-low breast cancer cells." (PMID 31717460, 2019). "It has been reported that CLDN1 expression levels were decreased in breast cancer, colorectal carcinoma, glioblastoma, and melanoma brain metastasis." (PMID 30910845, 2019). "But recently, some studies showed that the expression level of CLDN1 was low in luminal-like and claudin-low breast cancers, while the expression level of CLDN1 was high in basal-like, most ER negative, BRCA1, medullary breast cancers." (PMID 30910845, 2019). "There is a significant correlation between down regulation of CLDN1 expression and methylation of its promoter CpG-island in estrogen receptor positive breast cancer." (PMID 29169318, 2017). "Whereas, the different phenomenon was observed in breast cancer, hypermethylation and reduced expression of CLDN1, suggesting that the expression of CLDN1 varies in different tissues." (PMID 29221203, 2017). "In others, such as esophageal squamous cell carcinoma, lung, prostate, melanocytic neoplasia and breast cancers, claudin 1 appears to demonstrate tumor suppressor activities." (PMID 27649506, 2016). "Recently, a novel claudin-1 high expression group of mammary carcinomas has been identified, attributing a dual, tumor suppressor and oncogenic role in breast cancer." (PMID 26980408, 2016). "Upon knocking down these claudins, all except claudin-1 increased breast cancer cell migration with claudin-12 generating the most effects." (PMID 27547510, 2016). "The claudin 1 tight junction protein, solely responsible for the barrier function of epithelial cells, is frequently down regulated in invasive human breast cancer." (PMID 27649506, 2016). "For example, decreased expression of claudin-1, -2, and -7 coincides with more intrusive breast carcinoma." (PMID 27547510, 2016). "In particular, this was observed in the luminal-like ER+ breast cancers which exhibits low CLDN1 expression." (PMID 27649506, 2016). "On contrary, the expression levels of E-cadherin, ck8/18, claudin-1 were increased in the breast cancer cell lines after hsa-miR-195 overexpression." (PMID 26632252, 2015). "Silencing CLDN1 using lentiviral vector mediated RNA interference leads to reduced cell proliferation, migration, and invasion in breast cancer cell lines." (PMID 26067567, 2015). "Previous studies demonstrated that Snai2 is a transcriptional repressor of CLDN1 in epithelial breast cancer cells." (PMID 26067567, 2015). "Further investigation is required to elucidate the role of CLDN1 with the development of breast cancer." (PMID 26067567, 2015).
breast carcinoma (continued). "In breast cancer claudin 1 co-localized and directly interacted with membrane type MMP-1 and pro-MMP-2 and mediated its activation." (PMID 26633531, 2015). "Previous studies have shown that aggressive breast cancer is characterized by upregulation of claudin-3 and -4 and downregulation of claudin-1 and -7 proteins." (PMID 25871476, 2015). "Breast cancer cell migration was significantly reduced in cell lines transduced with either CLDN1 lentiviral shRNA vector as compared to cells transduced with SC control following scratching and 24 h culture." (PMID 26067567, 2015). "In future studies, we will examine the effect of CLDN1 expression in orthotopic breast cancer xenograft mouse model by injecting CLDN1 stable cell lines generated using lentiviral vector mediated RNA interference." (PMID 26067567, 2015). "In this study, we tested the therapeutic potential of silencing CLDN1 expression in two breast cancer (MDA-MB-231 and MCF7) cell lines using lentiviral vector mediated RNA interference." (PMID 26067567, 2015). "Understanding the interactions of the Eph family, their ligands and claudin 1 will be an important novel area of study with regards to breast cancer progression." (PMID 26633531, 2015). "In human breast cancer cell lines we have shown that either overexpression or inhibition of claudin 1 can alter the expression of EMT related molecules." (PMID 26633531, 2015). "Our data demonstrated that lentiviral vector mediated CLDN1 RNA interference has great potential in breast cancer gene therapy by inhibiting EMT and controlling tumor cell growth." (PMID 26067567, 2015). "In particular, we showed that the knockdown of claudin 1 in a basal-like subtype human breast cancer cell line, resulted in reduced cancer cell migration." (PMID 26633531, 2015). "In aggressive breast cancer, expression of claudin-3 and -4 have been shown to be upregulated, while claudin-1 and -7 proteins were downregulated, suggesting that individual claudin family members play different roles in breast carcinogenesis." (PMID 25871476, 2015). "These authors showed that Stanniocalcin 2 (STC2) promoted breast cancer metastasis in mice through its interaction with claudin 1, which directly led to an alteration of the expression of the EMT molecules including Zeb1, Slug, and Twist." (PMID 26633531, 2015). "In this review we highlight new insights into the role of claudin 1 in breast cancer, including its involvement in collective migration and epithelial mesenchymal transition (EMT)." (PMID 26633531, 2015). "Silencing CLDN1 inhibits EMT in both MDA-MB-231 and MCF7 breast cancer cells, indicating that CLDN1 is associated with tumor metastasis." (PMID 26067567, 2015). "In breast cancer, the interaction of claudin 1 with CD9 has been shown to coincide with its subcellular co-localization in breast cancer." (PMID 26633531, 2015). "CLDN1 showed antiapoptotic effects in MCF7 breast cancer cells, while silencing CLDN1 promotes beta-catenin and E-cadherin expression." (PMID 26067567, 2015). "We found that a CLDN1 short hairpin (shRNA) construct efficiently silenced CLDN1 expression in both breast cancer cell lines, and CLDN1 knockdown resulted in reduced cell proliferation, survival, migration and invasion." (PMID 26067567, 2015). "We have found that CRISPR/cas9 can efficiently silence the CLDN1 expression in breast cancer cell lines." (PMID 26067567, 2015). "CLDN1 was differentially expressed during pregnancy, lactation, and involution in the normal mammary gland and mammary tumors." (PMID 26067567, 2015). "The expression of other claudin family members, such as CLDN1 in podocyte and breast cancer and CLDN4 in bladder cancer, has also been reported to be regulated through promoter hypermethylation." (PMID 25277196, 2014). "They found that the expression of DEC1 is positively correlated with grade of breast cancer and negatively correlated with the expression of claudin-1." (PMID 24758579, 2014).
breast carcinoma (continued). "Claudin 1 expression is highest in some ER-samples, which is consistent with previous reports showing elevated claudin 1 expression in this subtype of breast cancer." (PMID 23844228, 2013). "More importantly, our studies strongly suggest that claudin 1 directly participates in promoting breast cancer progression, possibly through the alteration of expression of EMT genes." (PMID 23721519, 2013). "Claudin-1 knockdown in basal-like breast cancer cells decreases cell migration by affecting the expression of genes involved in EMT." (PMID 24009024, 2013). "Breast cancer cell lines recapitulate these phenotypes and we identified cell lines in which claudin 1 is silenced through promoter methylation as well as others in which claudin 1 is not silenced and is instead overexpressed." (PMID 23844228, 2013). "To investigate if silencing of claudin 1 has an epigenetic etiology in breast cancer we compared gene expression and methylation data from 217 breast cancer samples and 40 matched normal samples available through the Cancer Genome Atlas (TCGA)." (PMID 23844228, 2013). "Our analysis of the TCGA data shows that there is a significant correlation between downregulation of claudin 1 expression and methylation of its promoter CpG island in a subset of breast cancer." (PMID 23844228, 2013). "Claudin-1 is known as an anti-apoptotic factor and tumor suppressor as well as a tumor enhancer/facilitator in breast cancer cells." (PMID 23626786, 2013). "For instance, in breast cancer Cldn-1, -2, and -7 are downregulated, while Cldn-4 is upregulated and in colorectal- and pancreatic-cancer Cldn-1, -2, and -7 are upregulated." (PMID 23390516, 2013). "On the other hand, claudin-1 has an anti-apoptotic effect in tamoxifen-treated human breast cancer MCF-7 cells." (PMID 24009024, 2013). "Many of these tumors also displayed mislocalization of claudin 1 to the cytoplasm, suggesting that the role of claudin 1 in the breast cancer cell is influenced not only by its level but by its location as well." (PMID 23721519, 2013). "As in breast cancer, in which reduced expression correlated with recurrence status, the low expression of CLDN1 and other tight junction proteins seems to contribute to cellular detachment." (PMID 20805891, 2010). "Here, we showed for the first time the anti-apoptotic effect of claudin-1 in human breast cancer MCF-7 cells." (PMID 20937153, 2010). "In a previous study, the mRNA expression of claudin-1 was decreased in the tumor group compared with the control (normal) group in breast cancer tissues." (PMID 20937153, 2010). "We investigated the endogenous expression of claudin-1 in two breast cancer cell lines by Western blotting." (PMID 20937153, 2010). "In the present study, we investigated the relationship between claudin-1 and tamoxifen treatment in human breast cancer MCF-7 and T47 D cells." (PMID 20937153, 2010). "In breast cancer, the expression, localization, and function of Cldn1 differ according to the molecular subtypes of the cancer, suggesting that Cldn1 may function differently depending on the cellular context and differentiation status." (PMID 40361399, 2025). "Thus, CLDN1 appears to act as a metastasis suppressor in breast cancer, and its expression is a predictor of prognosis." (PMID 40687428, 2025). "Thus, CLDN1 behaves as a metastasis suppressor and chemo-sensitizer in breast cancer: its absence promotes EMT and invasion, while its expression helps maintain epithelial adhesion and chemosensitivity." (PMID 40687428, 2025). "Additionally, upregulation of CLDN1 has also been observed to activate the ERK signaling pathway in the MCF7 breast cancer cell line, further emphasizing its role in cancer progression." (PMID 40507913, 2025).
breast carcinoma (continued). "The transcription factors Slug and Snail have been found to act as repressors of CLDN1 expression in epithelial cells from human breast cancer, affecting tissue permeability and highlighting CLDN1 as a downstream target gene of the Snail family of transcription factors." (PMID 40871639, 2025). "CLDN1 has been described as downregulated in luminal breast cancer, but upregulated in aggressive basal-like subtypes, which may potentially suggest subtype switching for cells expressing ESR1-YAP1 or other ER fusions." (PMID 39207954, 2024). "CLDN1 is connected to the development of cancer, such as colon and breast cancer." (PMID 38520221, 2024). "Importantly, CLDN1 is pinpointed as a direct transcriptional target of Hh pathway activation in breast cancer, as evidenced by the correlation between membranous CLDN1 expression and Hh paracrine pathway activation." (PMID 36672179, 2023). "In breast cancer in general, claudin-1 is hypothesized to play a double role, first as a tumour suppressor on one hand, where its downregulation resulted in breast cell tumourigenesis." (PMID 37102018, 2023). "Moreover, CLDN1 expression induced apoptosis in MDA-MB-361 breast cancer cells and in MDA-MB-231 and Hs578T, two TNBC “claudin-1-low” cell lines." (PMID 36291810, 2022). "In breast cancer, CLDN1 expression levels vary in pathology subtypes." (PMID 36620607, 2022). "Little is known on CLDN1 role on the chemosensitivity in breast cancer." (PMID 36291810, 2022). "Little is known about CLDN1 role on the chemosensitivity of breast cancer." (PMID 36291810, 2022). "Fucoidan intake has been found to restore the microbiota and intestinal barrier function by regulating tight junction-associated proteins (ZO-1, occludin, claudin-1, and claudin-8) and the MAPK signaling pathway in a 7,12-dimethylbenz[a]anthracene (DMBA)-induced breast cancer rat model." (PMID 35719088, 2022). "Claudin-1 overexpression brings morphological changes and increases the intercellular adhesion through the disappearance of stress fibers, resulting in the migration inhibition of breast cancer mesenchymal-stem-like subtype cells." (PMID 34354941, 2021). "The expression of claudin-1 in breast cancer seems to be also modulated by a hormonal response." (PMID 32197343, 2020). "While one study reported that the activation of CLDN-1 was repressed by the binding of E-cadherin to CLDN-1 promoter, knockdown of CLDN-1 has been found to be associated with decreased cell migration and induction of EMT in breast cancer cells." (PMID 31952355, 2020). "Several transcript variants for CLDN-1 were found in human invasive breast cancer as a result of splicing and mis splicing events suggesting that through alternative splicing CLDN-1 is downregulated in invasive type of breast cancers." (PMID 31952355, 2020). "Moreover, the expression of certain key elements of EMT, including ZEB1, fibronectin, and claudin-1 in breast cancer cells were examined in vitro after treatment with SFN." (PMID 32309226, 2020). "Notably, claudin-1 (CLDN1) is downregulated in several cancers, and this correlates with recurrence or metastatic phenotype of lung adenocarcinoma, gastric cancer, breast cancer, melanoma, and colon cancer 22-26." (PMID 32754286, 2020). "Further, CLDN-1 overexpression in MDA-MB 361 breast cancer cells resulted in increased apoptosis." (PMID 31952355, 2020). "The CLDN-1 expression level in breast cancer differs depending on the cancer subtypes." (PMID 31952355, 2020). "Furthermore, RRP1B mediated DOCK1 depletion, which up-regulated claudin-1 expression, cell viability, and motility in claudin-low breast cancer cells." (PMID 31717460, 2019). "Whether CLDN1 plays tumor-facilitating role in basal-like breast cancer or TNBC still needs to be proved." (PMID 30910845, 2019). "CLDN1 has long been considered as a tumor suppressor in breast cancer." (PMID 30910845, 2019).
breast carcinoma (continued). "Introduction of shRNA targeting the 3′UTR of ADAM15 into T47D cells down-regulated endogenous ADAM15 expression, leading to a concomitant decrease in Claudin-1 levels confirming that ADAM15 is responsible for driving Claudin-1 expression in these breast cancer cells." (PMID 31467400, 2019). "Opposite colon cancer, claudin-1 is frequently down-regulated in invasive human breast cancer." (PMID 31861759, 2019). "It is tempting to speculate that ADAM15 mediated Claudin-1 upregulation might have a role in defining the metastatic niche, enhancing breast cancer cell attachment to hepatocytes and metastasis to the liver." (PMID 31467400, 2019). "CLDN1, is associated with apoptosis, EMT, and prognosis in breast cancer." (PMID 30543688, 2018). "Furthermore, it was also shown that depletion of EVI1 variants leads to increased claudin-1 expression, which leads to alterations in EMT marker expression that modulates cellular motility in both breast cancer and ovarian cancer cells." (PMID 29339729, 2018). "Recent reports suggest that hypermethylation may be a partial mechanism of CLDN1 silencing in breast cancer." (PMID 27649506, 2016). "However, an up regulation of CLDN1 in specific breast cancer subtypes, including the highly aggressive basal-like breast cancer, has now been demonstrated by us and others." (PMID 27649506, 2016). "Altogether, these studies suggest that epigenetic factors may play a role in CLDN1 regulation in breast cancer." (PMID 27649506, 2016). "However, high levels of claudin 1 have recently been demonstrated in a small but significant group of breast cancers, including the largely aggressive basal-like subtype." (PMID 27649506, 2016). "This study showed that exogenous IL-18 could enhance breast cancer cell migration and inhibit the expression of claudin-1, 3, 4, and 12 in human breast cancer cell line MCF-7." (PMID 27547510, 2016). "Silencing CLDN1 in the BT-20 breast cancer cell line inhibited cell migration and EMT." (PMID 26067567, 2015). "As well, miRNA regulation may be another possible mechanism by which claudin 1 is deregulated in breast cancer." (PMID 26633531, 2015). "Both in vitro and in vivo studies reveal an emerging role for claudin 1 in breast cancer." (PMID 26633531, 2015). "We investigated the role of CLDN1 by examining two subtypes of breast cancer using a luminal A subtype of breast cancer cell line MCF7, which was positive for estrogen (ER) and progesterone receptors (PR), negative for Her2 and a basal-like subtype MDA-MB-231 cells, and negative for ER, PR and Her2." (PMID 26067567, 2015). "Taken together, these studies indicated that CLDN1 may play a dual role and can function as a tumor suppressor or oncogene depending on the breast cancer subtype." (PMID 26067567, 2015). "Based on these observations, we conclude that STC2 suppresses EMT to hinder cell migration and invasion via the PKC/Claudin-1-mediated signaling, which may be useful for breast cancer diagnosis and treatment." (PMID 25830567, 2015). "It is therefore plausible that miR-155 may play a role in down regulating claudin 1 in breast cancer." (PMID 26633531, 2015). "However a direct role for claudin 1 in altering the migration and proliferation rates of several human breast cancer cell lines, has now been demonstrated." (PMID 26633531, 2015). "Collectively, these results indicate that STC2 may inhibit EMT at least partially through the PKC/Claudin-1-mediated signaling in human breast cancer cells." (PMID 25830567, 2015). "However, high expression levels of CLDN1 were found in the aggressive basal-like breast cancer subtypes." (PMID 26067567, 2015). "CLDN1 was shown to have an antiapoptotic effect in MCF7 breast cancer cells." (PMID 26067567, 2015).